CP (ceruloplasmin)
Diseases named in the same sentence as CP in open-access papers (continued):
Sharing a sentence is not in itself a finding about the gene and the disease.
cognitive decline (9 papers, 2019 to 2026). "Consistent with both Cu and Fe balance abnormalities, ceruloplasmin in the CSF has been shown to predict cognitive decline and brain atrophy in people with underlying Aβ pathology." (PMID 34566573, 2021). "Chronic exposure to copper in people susceptible to copper dyshomeostasis, as revealed by higher than normal levels of non-ceruloplasmin copper, has been linked to accelerated cognitive decline and an increased risk of AD." (PMID 32545484, 2020). "In addition, ceruloplasmin has been shown to predict cognitive decline and brain atrophy in people with underlying Aβ pathology when evaluated in the CSF or when measuring ceruloplasmin specific activity in serum." (PMID 36139084, 2022). "Dysregulation of systemic copper (Cu) metabolism, especially an elevated level of non-ceruloplasmin-bound copper (NCC), has been linked to oxidative stress and early cognitive decline." (PMID 42074984, 2026).
Insulin resistance (9 papers, 2015 to 2025). Increased resistance towards insulin, that is, diminished effectiveness of insulin in reducing blood glucose levels. "However, from our perspective, the co-occurred changes within the core of AFM, CP, and CFH were a secondary response to insulin resistance and might be caused by other dependent reasons." (PMID 33184417, 2020). "Since available data also suggest that Cu and ceruloplasmin may also be involved in NAFLD pathogenesis, it will be an important agenda of research to elucidate details of the interaction of iron and Cu with oxidative stress, insulin resistance, and histological damage in longitudinal studies." (PMID 26273604, 2015).
liver failure (9 papers, 2018 to 2025). A liver disease characterized by the liver losing or has lost all of its function. "Particularly, those with liver failure had lower serum ceruloplasmin levels (0.168 g/L, IQR 0.141~0.236), and 66.40% (83/125) of the patients had ceruloplasmin levels <0.20 g/L." (PMID 36570465, 2022). "53.0% of patients with liver failure, 37.7% of patients with nephrotic syndrome, and 23.0% of patients age 1 to 6 months had serum CP <200 mg/L." (PMID 29324775, 2018). "Moreover, other multiple diseases besides HLD have shown reduced serum ceruloplasmin levels, including liver failure, nephrotic syndrome, malnutrition, acquired copper deficiency, and genetic ceruloplasmin deficiency, among others." (PMID 40438368, 2025). "In patients with severe liver failure, marked hemolysis is frequently seen (in around 50–80% of cases) and may result from increased non-ceruloplasmin-bound copper released from impaired hepatocytes." (PMID 36673066, 2023). "Identifications of spots of interest by tandem mass spectrometry revealed that many were either known biomarkers for inflammation (complement components), or had previously been suggested as biomarkers for kidney failure (haptoglobin) or liver failure (ceruloplasmin)." (PMID 31568522, 2019). "The copper-overloaded LEC rats exhibited a severe hepatic failure associated with the enhanced serum levels of alanine transaminase (ALT) and aspartate aminotransferase (AST), increased serum level of total bilirubin, and reduced serum level of ceruloplasmin." (PMID 30733544, 2019). "Finally, a sudden marked decrease in ceruloplasmin was observed that could be indicative of imminent liver failure, a complication often observed in sepsis." (PMID 31568522, 2019). "Although patients with liver failure may have a low CP level, as many as 53.0% of patients with liver failure with CP <200 mg/L have not been reported." (PMID 29324775, 2018). "As severe overlap in CP concentration between WD and non-WD liver failure exists, WD could not be confirmed or excluded according to the CP concentration alone." (PMID 29324775, 2018). "Hence, the package insert indicated that no modification is required for CP A and B. No study is available in CP C. Using afatinib in CP C patients may exacerbate liver failure, as 9.7% of patients experienced liver test abnormalities and 0.2% of those cases were fatal in regular usage of afatinib." (PMID 40729346, 2025).
prostate carcinoma (9 papers, 2011 to 2024). A carcinoma that arises from epithelial cells of the prostate gland. "The clustering yielded a clear pattern of the five upregulated EV proteins (i.e., SERPINA3, SCGB3A1, LRG1, SERPINA6, and CP) enriched in the prostate cancer cases." (PMID 36500247, 2022). "Serum ceruloplasmin could complement biochemical screening in prostate carcinoma, especially in cases without elevated serum PSA." (PMID 28423673, 2017). "While we did not detect a separate hillock cell population within our prostate cancer epithelial cells, we did detect a distinct population representing 6.5% of all epithelial cells (872 of 13,322) characterized by expression of PIGR, MMP7, CP, and LTF (FDR q < 10e-20)." (PMID 35013146, 2022).
schizophrenia (9 papers, 2008 to 2026). A major psychotic disorder characterized by abnormalities in the perception or expression of reality. "In some schizophrenia studies, plasma ceruloplasmin was associated with subtypes, duration, severity, and antipsychotic treatment of schizophrenia." (PMID 19017404, 2008). "Our study suggests that low CP levels may aggravate executive dysfunction, indicating that CP deficiency might be a biological marker of executive dysfunction in schizophrenia." (PMID 40896216, 2025). "Ceruloplasmin abnormalities have been implicated in schizophrenia, even the nature of relationship remains unclear." (PMID 19017404, 2008). "The objective of this study to explore whether there is an association of ceruloplasmin with OCD as in schizophrenia." (PMID 19017404, 2008). "As in schizophrenia, association between ceruloplasmin and OCD might be examined through ceruloplasmin and copper relationship, since there is now growing evidence that the dopamine system may be involved also in the pathophysiology of OCD." (PMID 19017404, 2008). "There are numerous studies reporting an association between ceruloplasmin and schizophrenia, but the nature of the relationship remains unclear." (PMID 19017404, 2008). "In addition, ceruloplasmin has been associated with some clinical features of schizophrenia." (PMID 19017404, 2008). "For example, both schizophrenia and the FA of the left CP colocalized with the expression of the PCLO (ENSG00000186472) gene at chr7:82,503,409-82,616,835 (schizophrenia: PP.H4 = 0.828; left CP: PP.H4 = 0.819)." (PMID 41522603, 2026). "For example, both schizophrenia and the FA of the left CP colocalized with the expression of the PCLO gene." (PMID 41522603, 2026). "A study published in Schizophrenia Research measured the plasma ceruloplasmin levels in 10 patients with schizophrenia and found them to be significantly higher than those in the healthy control group." (PMID 40896216, 2025). "Increased serum ceruloplasmin has been reported in patients with psychiatric conditions, notably schizophrenia and OCD." (PMID 33062249, 2020). "L13a mediated translational silencing of ceruloplasmin expression seems to be beneficial for the brain, since ceruloplasmin up-regulation has been correlated with neurodegenerative diseases like schizophrenia and obsessive compulsive disorders." (PMID 26863456, 2016). "A systematic review incorporating 59 articles compared serum trace element levels, including ceruloplasmin, between schizophrenia patients and healthy controls, revealing significantly different serum ceruloplasmin levels in schizophrenia patients compared to the healthy control group." (PMID 40896216, 2025). "Since abnormalities in copper metabolism may lead to dopaminergic dysregulation, the ceruloplasmin and copper relationship might be important in schizophrenia." (PMID 19017404, 2008). "Several studies indicate that elevated serum ceruloplasmin levels may play a role in schizophrenia by exacerbating or perpetuating dopaminergic dysregulation." (PMID 19017404, 2008). "The objective of this study is to explore, whether there is a role of ceruloplasmin in OCD as in schizophrenia." (PMID 19017404, 2008). "Moreover, brain iron is thought to be modulated by ceruloplasmin, a multi-copper ferroxidase, and consistent with correlational data in rodents, a positive effect of copper on iron levels was evident across both control individuals and schizophrenia cases." (PMID 36750734, 2023). "We found that regardless of whether schizophrenia patients had normal or low serum ceruloplasmin (CP) levels, their executive function was significantly lower than that of healthy individuals." (PMID 40896216, 2025). "Furthermore, symptoms of psychosis and schizophrenia-like behaviour have also been reported in selected cases with aceruloplasminemia, a condition characterised by a complete absence of functional ceruloplasmin." (PMID 33062249, 2020).
viral hepatitis (9 papers, 2011 to 2025). An acute or chronic inflammation of the liver parenchyma caused by viruses. "In the situation with elevated aminotransferases, the mean level of serum ceruloplasmin in the 249 asymptomatic WD patients (5.5 ± 4.7 mg/dL) was significantly lower than that in the 38 patients with viral hepatitis (32.5 ± 7.9 mg/dL) (p < 0.001)." (PMID 35296237, 2022). "We, therefore, performed a viral hepatitis serology screen and tested for ceruloplasmin in serum of the patient." (PMID 28344651, 2017). "Fatty liver disease indicated by ALT or a combination of ALT and ultrasound, or liver biopsy,ANDTest for exclusion of other main causes of liver steatosis (e.g., serum lactate, iron, ferritin, pyruvate, copper, ceruloplasmin, alpha 1-antitrypsin level, viral hepatitis panel, liver autoantibodies)." (PMID 41230444, 2025).
autoimmune liver disease (8 papers, 2023 to 2025). "No abnormalities were observed in viral serologies (HBV and HCV), hemolysis test, coagulation function, autoimmune liver disease-associated antibodies, immunoglobulin G, serum ceruloplasmin testing, or abdominal ultrasound examination." (PMID 40901525, 2025). "For the diagnosis of cryptogenic cirrhosis, patients underwent extensive investigation, including viral serologies, alpha-1-antitrypsin, ceruloplasmin, urinary copper, immunoglobulins, autoantibodies for autoimmune liver diseases, protein electrophoresis, and imaging exams." (PMID 39201333, 2024). "The patient was negative for hepatitis virus, autoimmune liver disease antibodies, ceruloplasmin, and tumor markers." (PMID 39830503, 2025). "No hematologic disorders, autoimmune liver diseases, abnormal ceruloplasmin or serum ferritin, skin rash, or hepatosplenomegaly were detected." (PMID 36274106, 2023).
Hepatic steatosis (8 papers, 2017 to 2025). Steatosis is a term used to denote lipid accumulation within hepatocytes. "During aging, ceruloplasmin‐deficient (CpKO) mice display adipose tissue accumulation and liver steatosis." (PMID 37986139, 2024). "Indeed, serum ceruloplasmin levels were significantly associated with ballooning hepatocytes, inflammatory cells infiltration, and/or hepatic steatosis in pediatric NAFLD patients." (PMID 32674425, 2020). "Thus, HFD increases liver weight and causes liver hepatic steatosis in rats, and CP and HJF attenuate liver hepatic steatosis in HFD-fed rats." (PMID 29675053, 2018). "It is reported that downregulation of hepatic ceruloplasmin results in the restoration of hepatic copper level, which attenuates liver steatosis by targeting copper-SOC1-AMPK signaling pathway in NAFLD mice model." (PMID 36817887, 2023). "Oil red O staining and the positive rate of it showed that HFD group rats had serious hepatic steatosis, and this hepatic steatosis was notably alleviated in the CP and CR groups." (PMID 29675053, 2018). "Pathogenic variants were detected in the ABCB4 gene in a patient with idiopathic cholestasis, in the APOB and CP genes in a patient with hepatic steatosis, in the ABCB4 gene in a patient with elevated liver enzymes, and in the MTTP and AGL genes in a patient with cryptogenic cirrhosis." (PMID 40870862, 2025). "In one study, both Cu and serum ceruloplasmin were negatively associated with siderosis, ferritin, and HOMA-IR, but not liver steatosis." (PMID 35741222, 2022). "However, chronic hepatitis B patients with hepatic steatosis had higher ceruloplasmin levels in their sera than those without steatosis." (PMID 32674425, 2020).
malaria (8 papers, 2012 to 2025). Malaria is a serious and sometimes fatal disease caused by a parasite that commonly infects a certain type of mosquito which feeds on humans. "This raises intriguing questions about the potential diagnostic and prognostic role of ceruloplasmin in malaria-infected patients." (PMID 39574108, 2024). "The elevation of ceruloplasmin levels in malaria patients across different publication years underscores the consistency of the association between malaria and increased ceruloplasmin." (PMID 39574108, 2024). "Given that children are particularly susceptible to severe malaria, the elevated ceruloplasmin could potentially be explored as a marker for disease severity or progression in pediatric populations." (PMID 39574108, 2024). "The initially increased mRNA expression of C1ra, C1s, and C2 in the liver of vaccinated mice suggests that protective vaccination accelerates the complex malaria-induced initial activation patterns of CP and LP." (PMID 40243929, 2025). "In the current meta-analysis, an evident increase in ceruloplasmin levels was observed in patients diagnosed with malaria as compared to the uninfected controls." (PMID 39574108, 2024). "By amalgamating this information, the study aimed to offer insights into ceruloplasmin’s role in malaria pathophysiology and assess its potential utility in clinical settings." (PMID 39574108, 2024). "The meta-analysis showed a significant increase of ceruloplasmin in patients with malaria as compared to uninfected controls (P < 0.01, Hedge’s g 1.18, 95% CI 0.90–1.47, I2 59.19%, eight studies)." (PMID 39574108, 2024). "This subgroup analysis offers a more granular understanding of how ceruloplasmin levels vary in patients with malaria compared to uninfected controls, with regard to several factors." (PMID 39574108, 2024). "The majority of included studies found significantly increased ceruloplasmin levels in malaria patients compared to uninfected controls." (PMID 39574108, 2024). "Differences in study design, such as cross-sectional and case-control studies, both show elevated levels of ceruloplasmin in malaria-affected individuals." (PMID 39574108, 2024). "The subgroup analysis showed a comprehensive subgroup analysis, shedding light on variations in ceruloplasmin levels between malaria-infected individuals and uninfected controls, categorized by several factors." (PMID 39574108, 2024). "Further research is essential to understand the variations in ceruloplasmin levels between different Plasmodium species and the severity of malaria in patients." (PMID 39574108, 2024). "Differential abundance of LRG1 and CP was observed between dengue and malaria using MRM assays as well as in TMT-based quantitation." (PMID 33204009, 2020). "Furthermore, our data show the responses to malaria of both the CP and the LP to be also accelerated by vaccination." (PMID 40243929, 2025). "Furthermore, our data indicate that protective vaccination impacts, albeit differently, the activation of the three malaria-responsive complement pathways AP, LP, and CP." (PMID 40243929, 2025). "Recent reports are in line with these results, confirming increased CP activity in malaria." (PMID 24020374, 2013). "Quite a few differentially abundant proteins such as Haptoglobin (HP), Superoxide dismutase (SOD), Ceruloplasmin (CP), Titin (TTN), Nebulin (NEB), and Vitronectin (VTN) were found to be highly relevant in context of pathophysiology of severe malaria." (PMID 27090372, 2016). "Specifically, there was a more significant increase in ceruloplasmin levels in cases of severe malaria than non-severe cases." (PMID 39574108, 2024). "Interestingly, SAA, TTN, SOD and CP exhibited differential abundance (>1.5-fold up-regulated) between SVM and NSVM, indicating their potentiality as the predictive markers for malaria severity." (PMID 27090372, 2016).
malaria (continued). "CP and GR are significantly increased in malaria-infected individuals (with or without jaundice) on D1 and TrxR is lower in infected patients, compared to healthy volunteers." (PMID 24020374, 2013). "Interestingly, patients with malaria who were treated with chloroquine demonstrated a more significant increase in ceruloplasmin levels compared to those who did not receive any antimalarial therapy." (PMID 39574108, 2024). "In the analysis, when each study was systematically excluded from the meta-analysis and the analysis re-conducted, the consistent observation was that ceruloplasmin levels remained elevated in individuals with malaria compared to those without the infection across all iterations." (PMID 39574108, 2024).
myocardial infarction (8 papers, 2013 to 2025). Gross necrosis of the myocardium, as a result of interruption of the blood supply to the area, as in coronary thrombosis. "It was shown that a high level of ceruloplasmin in serum was associated with a higher risk of myocardial infarction after 3 years (HR 2.35, 95% CI 1.79-3.09, p < 0.001)." (PMID 36361589, 2022). "Many studies have shown that ceruloplasmin (CP) levels were elevated in patients with cardiovascular disorders including arteriosclerosis, coronary heart disease, and myocardial infarction." (PMID 23781119, 2013). "Scientists have examined the role of the copper-containing protein ceruloplasmin in heart attacks." (PMID 38618322, 2024). "Ceruloplasmin, a copper-containing protein, has been studied by researchers in heart attacks." (PMID 38618322, 2024). "Compared to myocardial ischemia-reperfusion (IR) or VA-ECMO support for 30 min before reperfusion, Impella CP device activation before reperfusion reduced myocardial infarct size (51 ± 14% vs 62 ± 15% vs 33 ± 7%, IR, VA-ECMO, Impella, respectively, p < 0.05 for Impella vs either group)." (PMID 33782857, 2022). "Ceruloplasmin, an enzyme containing copper that participates in various bodily processes, and uric acid, a byproduct of purine metabolism, might have a role in developing myocardial infarction." (PMID 38618322, 2024).